IL27 (interleukin 27)
Diseases named in the same sentence as IL27 in open-access papers (continued):
Sharing a sentence is not in itself a finding about the gene and the disease.
tumor (continued). "Evidence has revealed that IL-27, an immune regulator cytokine, can contribute to anti-tumor responses in several cancers without noticeable toxicity." (PMID 34868907, 2021). "An important number of cytokine levels were below the detection limit of the method (LOD and/or LLOQ) such as IL-2, IL-10, IL-11, IL-12 (p40), IL-12 (p70), IL-19, IL-27 (p28), IL-28A/IFN-λ2, IL-29/IFN-λ1, IFN-α2 and osteocalcin in both tumor and normal tissue control samples." (PMID 33846436, 2021). "IL-27 induces a set of proteins broadly overlapping with those induced by IFN-γ and shares several anti-tumor functions in common with IFNs, including anti-angiogenic activities, induction of HLA-class I molecule expression, and anti-proliferative activity on cancer cells." (PMID 34439164, 2021). "On the other hand, the induction of PD-L1 and IDO1 expression may dampen the anti-tumor CTL response, suggesting that IL-27 and IFN-γ may have dual effects in tumors." (PMID 32093058, 2020). "In human monocytes, IL-27 also upregulates HLA-E, which, upon interacting with CD94/NKG2A, suppresses the NK cell functions and IFNγ release which, in turn, weakens the anti-tumor immunity." (PMID 32143355, 2020). "Moreover, IL-27 has been shown to enhance the activation and proliferation of CD8+ T cells and to trigger anti-tumor functions in γδ T cells, thus also affecting T cell subsets that were elevated upon DOX/anti-PD-1 treatment in our study." (PMID 33014872, 2020). "Although the role of IL-27 in tumor immunity has been appreciated for more than a decade, developing IL-27 into a therapeutic to enhance tumor immunity has not been well achieved." (PMID 32292786, 2020). "However, the selective IL-30 blockade in PC–SLCs, which are unable to release detectable EBI3 and IL-27, led to a considerable anti-tumor efficacy with a clear implication for myeloid cells, whose ability to home to the tumor site is dramatically lost." (PMID 32143355, 2020). "We examined blood IL-27 levels in two typical mice whose tumors were not rejected or completely rejected, and found that tumor rejection also resulted in IL-27 reduction." (PMID 32292786, 2020). "The data again indicated a decreased cytotoxicity of IL-27Ra KO NK cells toward PyMT tumor cells and, more importantly, revealed an enhanced cytotoxicity of WT NK cells, but not IL-27Ra KO NK cells, when supplemented with recombinant IL-27." (PMID 33014872, 2020). "Since IL-27 regulates the balance of Th1 and Th2 cells, it has the potential to skew the CD4+T cell response toward Th1, which could enhance tumor regression." (PMID 31681561, 2019). "Like IL-27, expression of IL-35 can directly impact cancer cell survival by acting on tumor cells and due to its non-covalent heterodimeric nature, it is important to consider how IL-35 is delivered in the model system." (PMID 31681561, 2019). "Since these studies use EBI3 KO mice, these mice are lacking IL-27 and IL-35, thus potentiating a role for IL-30 in promoting Treg development and contributing to tumor progression." (PMID 31681561, 2019). "Interactions between IL-27, IL-30, and IL-35 subunits within the TME may influence tumor development and may contribute to immunotherapeutic outcomes." (PMID 31681561, 2019). "Therefore, the roles of IL-27 and TGF-β produced by M-MDSC in the tumor microenvironment deserves further investigations." (PMID 30936876, 2019). "The ability of IL-27 to limit TGF-β may serve to promote N1 polarization, while IL-35 has demonstrated the capacity to promote N2 polarization favoring tumor progression." (PMID 31681561, 2019). "The absence of IL-27 signaling severely limits the formation of functional blood vessels and thus, tumor angiogenesis." (PMID 31637217, 2019). "Although CXCL9 and CXCL10 are described as anti-angiogenic chemokines, their impact on the tumor vasculature under conditions of IL-27 treatment was not tested." (PMID 31637217, 2019).
tumor (continued). "Moreover, in lymphoid cells, IL-27 induces the expression of the transcription factor T-bet, an inducer of Th1 and CTL responses, which have been involved in the anti-tumor activity of IL-27." (PMID 29020964, 2017). "When a higher dose (100 μg) of poly(I:C) was injected, tumor progression was more markedly inhibited regardless of the combination with IL-27 (data not shown)." (PMID 24155891, 2013). "In addition, IL-27 and poly(I:C) cooperatively augmented TRAIL expression and inhibited tumor growth." (PMID 24155891, 2013). "Moreover, IL-27 increases TLR3 expression and therefore the combination of IL-27 and poly(I:C) cooperatively enhances TRAIL expression and inhibits tumor growth." (PMID 24155891, 2013). "In summary, WSX1's ability to promote tumor growth is not mediated via IL27, but via an alternate mechanism." (PMID 21559505, 2011). "The underlying mechanism by which WSX1 promotes tumor growth is dependent on the presence of an immune surveillance system and the pro-tumorigenic properties of WSX1 are independent of IL27." (PMID 21559505, 2011). "Direct co-incubation of WSX1-positive tumor cells and purified CD3+ T or NK cells inhibits T cell numbers or NK cell's ability to produce IFNγ whereas neither T, neither NK, nor tumor cells express IL27." (PMID 21559505, 2011). "If LLC-MUT-expressing tumors grew slower than full-length WSX1 in wildtype mice, then it indicates that IL27 promotes tumor growth; otherwise, IL27 does not explain pro-tumorigenic abilities of WSX1." (PMID 21559505, 2011). "To further verify the function of CAL-101 and whether IL-27 induces IL-10 expression, we detected the viral copy number and cytokine levels in the blood and tumor tissues at 8 and 72 hours after intravenous injection to the DT6606 subcutaneous tumor model." (PMID 40350204, 2025). "The authors extended this analysis to breast (E0771) and skin (B16-F10) syngeneic tumor models, which are poorly responsive to immune checkpoint inhibitors (ICI), and demonstrated that IL-27 was not effective as single treatment but synergized with ICI to control or delay tumor progression." (PMID 40254608, 2025). "Therefore, when considering the notably low (IL‐6 and IL‐27) and high (IL‐10) level of cytokines, as well as lower number of CD163+ cells, 2‐ME may also have rendered an anti‐tumor effects such as the greater tumor necrosis." (PMID 38600057, 2024). "Its impact on NK cells and their ability to regulate tumor growth has been observed in certain murine models, but not in all of them, suggesting that the effects of IL-27 on mouse NK cells may vary depending on the type of tumor." (PMID 39063193, 2024). "Finally, IL-27 showed an extraordinary ability to increase the regulation of PD-L2 and HLA-I expression on the tumor endothelium, while it did not modify that of PD-L1 and HLA-II." (PMID 36362718, 2022). "Based on our results, it appears that the effects of IL-27 as an adjuvant in a DTCV to develop anti-tumor responses are not long-lasting and could be due to the lack of establishing robust memory responses." (PMID 35529885, 2022). "In contrast, mLOAd703 treatment led to infiltration of the tumor by CD8+ T cells, natural killer (NK) cells, and CD103+ DCs, accompanied by a systemic increase of pro-inflammatory cytokines interferon γ (IFN-γ), tumor necrosis factor alpha (TNF-α), and interleukin-27 (IL-27)." (PMID 35141399, 2022). "Our previous research suggests that IL-27 significantly enhances the survival of tumor antigen specific CD8+ T cells in vivo, which indicates that AAV-IL-27 intra-tumoral administration could also be used as an adjuvant for T cell adoptive transfer therapy for cancer." (PMID 32292786, 2020). "This may not be surprising as these markers were only found in tumor infiltrating T cells and IL-27 may be mediating this profile." (PMID 32579593, 2020).
tumor (continued). "Also, IL-27-releasing DCs induced a proper microenvironment for cancer growth, since IL-27 promoted CCL22 production and consequently mediated the recruitment of Tregs to the tumor site." (PMID 29033934, 2017). "Finally, IL-27 showed a striking capability of up-regulating the expression of PD-L2 and HLA-I on tumor endothelium, whereas it did not modify that of PD-L1 and HLA-II." (PMID 28456791, 2017). "To determine the effects of TTP-mediated IL-27 inhibition on tumor development, we employed a murine mammary gland tumor model by inoculating E0771 cells into mammary gland pads of WT, Zfp36−/−, IL27ra−/− and TTP/WSX-1 DKO mice, followed by monitoring of tumor growth." (PMID 29021521, 2017). "Indeed, IL-27 has been shown to drive upregulation of HLA-I also in chronic eczema keratinocytes that produced IL-27, but it promoted PD-L1 expression in different cell types including CD4+ and CD8+ T cells, monocytes, DC and tumor cells." (PMID 28456791, 2017). "However, IFN-γ is a stronger inducer of PD-L1 expression than IL-27, in SCLC and may therefore limit anti-tumor responses by PD-1 expressing CTLs in vivo." (PMID 29020964, 2017). "In particular, GBP-1 is one of the most IL-27 up-regulated proteins and is also an important mediator of the IFN-γ-mediated inhibition of endothelial and epithelial tumor cell proliferation, migration, and invasion, which results in anti-angiogenic and anti-tumor effects." (PMID 27683036, 2016). "IL-18BP is expressed in primary EOC and tumor-associated leukocytes in vivo, but not in human EOC cell lines, where it may be induced by stimulation with IFN-γ or IL-27." (PMID 26657115, 2015). "Preclinical studies have revealed that the immune-regulatory cytokine IL-27 may exert anti-tumor activities in a variety of tumor types without discernable toxicity." (PMID 24681516, 2014). "Several lines of evidence suggest that IL-27 expression by tumor cells may not have an adverse outcome on tumor progression, but instead may favor this progression." (PMID 24130734, 2013). "In-vivo, LLC-MUT-expressing tumors grew faster than either WSX1 or GFP cohorts, excluding the role of IL27 as a tumor promoter, suggesting that IL27 signaling in tumors may inhibit tumor growth rather than promote tumor growth." (PMID 21559505, 2011). "Moreover, IL27 signaling in WSX1 positive tumor cells (LLC-WSX1) reduces rather than promotes tumor growth, consistent with other publications." (PMID 21559505, 2011). "While IL-27 supports EBV-transformed B-cell proliferation at doses secreted by infected cells in culture, we found that at high doses, IL-27 instead downmodulates EBNA expression, which might also provide anti-tumor effects by impairing transformed cell growth in vivo." (PMID 38683861, 2024). "However, the influence of tumor type on the detection of IL-27, especially IL-27-related tumors, could not be determined, so relevant studies are needed for verification." (PMID 36111237, 2022). "Hence, IL-27 and his co-enhancing partner IL-12 may not be active in the stages were neoplastic tissue is well differentiated into a tumor, as it is in the case of our cohort formed by patients with tumors beyond the IIA stage." (PMID 33846436, 2021). "We found that IL27 expression was inversely correlated with Breslow depth (Pearson correlation test; R = - 0.19, P = 0.00042) in 329 patients with complete Breslow depth value, and was significantly overexpressed in patients with tumor than in patients without tumor (t-test; P = 0.013)." (PMID 34733272, 2021). "Therefore, IL-27, similar to IFN-γ may facilitate CTL recognition by HLA-class I antigen presentation, and also exerts anti-proliferative effects by directly acting on human tumor cells, including, for example, EOC and multiple myeloma cells." (PMID 32093058, 2020).
tumor (continued). "Thus, the autocrine effect of IL-27 on tumor cells could not be observed in previous studies, which may in part account for the discrepancy between our in situ observations and the findings obtained using this murine model." (PMID 24130734, 2013). "These tolerogenic DCs present tumor antigen without proper costimulation (CD80/CD86), express inhibitory molecules (PDL1/CTLA4), and secrete immunosuppressive factors (TGF-β, IL-10, IL-27, NO, Arg, and IDO)." (PMID 35972798, 2022). "For example, although IL-27 can simultaneously activate STAT1 and STAT3, the activation of STAT1 rather than that of STAT3 mediates the tumor suppressor role of IL-27." (PMID 28626343, 2017). "These functions are attributed to IL27 but not IL30, the p28 subunit of IL27 which can function independently of IL27, because reconstitution with IL27 but not IL30 promotes tumor growth in an IL27R-dependent matter." (PMID 27738312, 2016). "Take together, our findings clearly demonstrate serum IL-6 rather than IL-27, TNF-α, and VEGF playing a definite role in liver deterioration and tumor progression, as well as further affecting HCC patient survival." (PMID 25908103, 2015). "Exhausted T cells from chronic infection however are not affected by IL-27 signaling and thus PROCR and PDPN expression may depend on the tumor microenvironment and not characterize all exhausted CTL." (PMID 32579593, 2020). "Using genetically modified tumor cells, we present evidence that the overexpression of WSX1 in two independent tumor models, such as aggressive Lewis Lung Carcinoma (LLC) and melanoma cell line AGS, promotes tumor growth independent of IL27 signaling." (PMID 21559505, 2011). "IL-27, with its diverse influences on immune responses, has not been studied extensively in nonmelanoma skin cancers (NMSC), including Squamous and Basal Cell Carcinomas (SCC and BCC), and its roles in tumor initiation, progression, and its probable use in NMSC treatment have yet to be unveiled." (PMID 30581461, 2018). "IL-27 may thus represent a potential tool for immunotherapy not only because it induces Th1/CTL responses in vivo but also for its ability to up-regulate HLA class I expression on tumor cells and their recognition by CTLs." (PMID 27683036, 2016).
cancer (101 papers, 2010 to 2026). A tumor composed of atypical neoplastic, often pleomorphic cells that invade other tissues. "In this review, we will discuss the immunobiology and functions of IL-30 and IL-30-associated cytokines (primarily IL-27) in the settings of inflammation and cancer." (PMID 34045653, 2021). "Here, we showed the association of IL27 with pyroptosis, providing evidence of the mechanism underlying IL27 function in cancer." (PMID 34733272, 2021). "In this study, we conducted a comprehensive meta-analysis of all eligible studies to derive a more precise estimation of the relationship between IL-27 polymorphism and cancer risk." (PMID 32986346, 2020). "So we conducted the present meta-analysis of eligible published studies to further assess the association between the IL-27 polymorphisms and cancer risk." (PMID 32986346, 2020). "After pooling all the available data, the finding suggested that IL-27 rs153109 (-964 A>G) significantly increased the risk of overall cancer." (PMID 32986346, 2020). "Several studies examined the association between IL-27 polymorphisms and the risk of various cancer." (PMID 32986346, 2020). "The findings did not support an association between rs17855750 T>G, rs181206 T>C polymorphisms of IL-27 and cancer risk." (PMID 32986346, 2020). "the current study findings suggest that IL-27 rs153109 polymorphism significantly increased the risk of cancer susceptibility." (PMID 32986346, 2020). "The current meta-analysis aimed to address the association between IL-27 rs153109, rs17855750, and rs181206 polymorphisms and the risk of cancer." (PMID 32986346, 2020). "In conclusion, the findings of this meta-analysis provide evidence for an association between IL-27 rs153109 polymorphism and cancer risk." (PMID 32986346, 2020). "In our previous studies of the TMEs of several different cancer types, we found that elevated levels of transcripts for the cytokines IL-1a, IL-10, IL-27 and IL-32 g, in addition to IFN-g, were associated with PD-L1 protein expression." (PMID 31730010, 2019). "IL-27 has been implicated in promoting cancer progression, as it can promote proliferation of human leukemic cell lines." (PMID 31681561, 2019). "The associations between polymorphisms of IL-27 gene and human diseases, including cancers, have been widely studied." (PMID 26014498, 2015). "Few studies have investigated polymorphisms and serum/plasma levels of IL-27 in diseases including cancers." (PMID 26014498, 2015). "Recently, it has been reported that an adeno-associated virus expressing IL-27 (AAV-IL-27) could induce the depletion of regulatory T (Treg) cells to enhance the efficacy of cancer immunotherapy." (PMID 40350204, 2025). "A relationship between IL-27 genetic polymorphisms and cancer risk has been identified." (PMID 33418929, 2021). "Several epidemiological studies have designated that genetic variants of the IL-27 gene may contribute to various cancer susceptibility, but the data were inconclusive." (PMID 32986346, 2020). "Second, this study focused on the impact of limited variants of IL-27 and cancer susceptibility." (PMID 32986346, 2020). "One possibility is that IL27-trained pre-malignant niche may affects mutated skin stem cells as cancer stem cells have been detected and described in many carcinogenesis models, including the skin." (PMID 27738312, 2016). "The presence of Th17 cells and IL-27 is observed in a variety of inflammatory associated cancers." (PMID 25969628, 2015). "Therefore, IL-27 may play an anti-inflammatory role in the pathogenesis of cancer-associated immunological abnormalities." (PMID 25969628, 2015). "Intriguingly, IL-27, which displays pleiotropic functions in cancer, was shown to inhibit AML and B-ALL progression in preclinical models." (PMID 41129238, 2026). "In conclusion, the authors’ findings highlight the potential of targeting the IL-27–IL-27RA axis to enhance ICI efficacy in cancer." (PMID 40254608, 2025).